CRP (C-reactive protein)
Diseases named in the same sentence as CRP in open-access papers (continued):
Sharing a sentence is not in itself a finding about the gene and the disease.
bacterial meningitis (continued). "For example, cytology using CSF or peripheral blood smears, detection of bacterial polysaccharides, as well as detection of blood markers such as C-reactive protein, are methods available in most hospital laboratories and often enable differentiation between viral or bacterial meningitis." (PMID 27357022, 2016). "Besides, several studies have demonstrated the existence of increased levels of C-reactive protein in cerebrospinal fluid and serum of patients with bacterial meningitis compared with patients with viral meningitis and control subjects." (PMID 26040285, 2015). "One recent study included 151 patients admitted to an adult emergency department with suspected of bacterial meningitis and a negative direct examination of CSF, to assess the diagnostic value of CRP, PCT, and CSF leucocytes count." (PMID 23830525, 2013). "However, recent studies have proposed that blood procalcitonin, CSF lactate, and blood C-reactive protein (CRP) are very good biomarkers for bacterial meningitis." (PMID 23209715, 2012). "In acute bacterial meningitis, CRP and pre – calcitonin rise in serum and CSF." (PMID 23483792, 2012). "Pleocytosis of CSF with greater than 10 WBC/ml and CRP>100ng/ml had 95% positive diagnostic value for bacterial meningitis; nevertheless, few patients with no or little WBC in CSF had low CRP in admission." (PMID 23483792, 2012). "As a result, serum CRP in bacterial meningitis is always detectable." (PMID 23483792, 2012). "Other markers, such as C-reactive protein (CRP) and procalcitonin, may allow differentiation of patients with bacterial meningitis from those with aseptic meningitis." (PMID 21194480, 2010). "Median CRP concentration in CSF in the overall cohort was 0.00 (IQR 0.00–0.58), with 1.63 mg/L (IQR 0.49–5.36) in bacterial meningitis, and 0.00 mg/L (IQR 0.00–0.00) in viral CNS infections." (PMID 40636058, 2025). "The median CRP concentration in CSF in the whole cohort was 0.00 (IQR 0.00–0.00), with 6.62 mg/L (IQR 3.37–14.4) in bacterial meningitis patients, and 0.00 mg/L (IQR 0.00–0.00) in all other patients." (PMID 40636058, 2025). "Median CRP concentration in CSF in the whole cohort was 0.00 (IQR 0.00–0.00), with 3.02 (IQR 1.40–8.42) in bacterial meningitis patients, and 0.00 (IQR 0.00–0.00) in all other patients." (PMID 40636058, 2025). "Another difference between bacterial meningitis and DIAM is the high level of C-reactive protein (CRP)." (PMID 37635233, 2023). "Other biomarkers, including lactate, C-reactive protein (CRP), and procalcitonin (PCT), are used to differentiate between bacterial and non-bacterial meningitis." (PMID 36864913, 2023). "The aims of this study, is retrospective comparison of WBC count, CRP, ESR, WBC and neutrophil count of CSF were independent variable that in regression model, these have 45% positive predictive value in bacterial meningitis and 93.2% PPV in viral." (PMID 23483792, 2012). "One patient without bacterial meningitis, with blood admixture in the CSF, had an elevated CRP concentration." (PMID 40636058, 2025). "None of the other laboratory parameters, including C-reactive protein, showed any significant difference among patients with viral or bacterial meningitis." (PMID 38333447, 2024). "Measurement of CRP in cerebrospinal fluid has a sensitivity of 100% and a specificity of 94% for differentiating between patients with bacterial meningitis, viral meningitis, and no infection." (PMID 29706967, 2018). "The peripheral WBC count, CRP, and ESR are usually elevated in patients with bacterial meningitis." (PMID 24803939, 2014). "As such, while an elevation in either CRP or procalcitonin is more suggestive of bacterial infection, neither can establish, nor exclude the diagnosis of bacterial meningitis." (PMID 23050153, 2012). "In five bacterial meningitis patients, CRP in CSF could not be detected, and in three patients with a viral CNS infection, CRP in CSF was elevated." (PMID 40636058, 2025).
bacterial meningitis (continued). "Antibiotic treatment may be discontinued once a positive EV PCR result is obtained and the clinical picture and laboratory findings (low CRP and leukocytes in blood, negative CSF bacterial cultures) indicate that bacterial meningitis is unlikely." (PMID 40703496, 2025). "However, in the subgroup of patients with a CSF leucocyte count 5-1,000/mm3, other biomarkers such as a combination of CRP and IL6 demonstrated better predictive accuracy in differentiating bacterial meningitis from other diseases and bacterial vs viral CNS infections." (PMID 40471671, 2025). "Of the two with positive CSF Gram stains (Gram-positive diplococci reported in both) there was no supporting microbiological evidence for a diagnosis of bacterial meningitis in one child, and in the other, enterovirus was detected with the viral RT-PCR while CRP was 2.8 mg/L." (PMID 28346504, 2017). "The NICE clinical guidelines (CG102) for the management of bacterial meningitis and meningococcal septicaemia in children and young people recommend non-specific laboratory tests including CRP and WCC as being useful investigations for those presenting with FWS." (PMID 26053385, 2015). "Meta-analysis from 35 studies proposed to use CRP as an additional tool for discriminating bacterial meningitis from viral meningitis, without having evaluated its independent contribution relative to other parameters such as white blood cell count, CSF white cell count, protein, or glucose." (PMID 24803939, 2014). "These authors found an AUROC of 0.91, 0.87, and 0.72 for CRP, PCT, and sCD 163, respectively, and concluded that CRP and PCT levels could be useful when combined with results of CSF examination to help diagnose bacterial meningitis." (PMID 23830525, 2013). "In one bacterial meningitis patient CRP in CSF could not be detected." (PMID 40636058, 2025). "C-reactive protein (CRP) and white cell count (WCC) measurement is recommended as a potential indicator of bacterial meningitis in febrile children with a rash although these are non-specific indicators of severe infection." (PMID 26053385, 2015). "In patients evaluated for neurological disorders in similar settings, CRP and PCT determination may contribute to discriminate invasive bacterial infections (mainly bacterial meningitis) from the numerous other infectious and non-infectious etiologies." (PMID 31664120, 2019).
viral pneumonia (53 papers, 2009 to 2026). Inflammation of the lung parenchyma that is caused by a viral infection. "Furthermore, features such as AGE, NEU%, RDW-SD, and CRP are strongly associated with the severity of viral pneumonia and the development of chronic lung sequelae." (PMID 40669043, 2025). "The CRP may also be used, yet its increase only differentiates bacterial from viral pneumonia, while the CRP/PCT ratio points to patients with an increased risk of atypical infection." (PMID 36233374, 2022). "We conducted this analysis to see if CRP could be a useful diagnostic to distinguish bacterial from viral pneumonia." (PMID 28575375, 2017). "CRP, in particular, has been shown to differentiate bacterial from viral pneumonia with modest sensitivity (70%) and specificity (65%), making it a valuable adjunct in the diagnostic process." (PMID 40115676, 2025). "In this group, the radiologic score was the most interconnected marker, correlating with CRP, ferritin, and D-dimer, supporting the suspicion of severe viral pneumonia and intense inflammation." (PMID 41156159, 2025). "Subsequent studies showed how the elevation of inflammatory markers, such as CRP and procalcitonin, helped to differentiate bacterial from viral pneumonia, including bacterial and viral infection pneumonia." (PMID 38475703, 2024). "For example, high CRP with fever increased specificity in distinguishing bacterial and viral pneumonia when compared to elevated CRP alone." (PMID 37763325, 2023). "Further, ZTO has also been shown to have an effect in children with viral pneumonia by significantly decreasing serum levels of IL-8, CRP, creatine kinase, and cardiac troponin." (PMID 36703758, 2022). "While compared the COVID-19 pneumonia with other viral pneumonia in the testing cohort, only C-reactive protein showed significant difference." (PMID 33413480, 2021). "Analysis of the early laboratory examination findings showed that elevation of the CRP and the percentage of monocytes, and decrease of the eosinophil count are common characteristics of the two forms of viral pneumonia." (PMID 32574297, 2020). "Combining elevated CRP with the presence or absence of clinical signs/ symptoms differentiates definite bacterial from presumed viral pneumonia better than CRP alone." (PMID 30940126, 2019). "A study in Finland showed that of the routine blood tests, only the C-reactive protein (CRP) level differed significantly between bacterial and viral pneumonia patients." (PMID 28702309, 2017). "Likewise, CRP values were significantly higher in those with bacterial/mixed pneumonia compared to those with viral pneumonia (60.8 ± 59.9 vs 39.5 ± 48.1 mg/dL, p = 0.016)." (PMID 38183438, 2024). "CRP is one of the best biomarkers to differentiate between bacterial and viral pneumonia." (PMID 38397359, 2024). "Secondly, procalcitonin, despite being a biomarker with a better predictive value compared to CRP or interleukin-6 in differentiating between bacterial and viral pneumonia, still has a rather low reported sensitivity and specificity, of 0.55 and 0.76, respectively." (PMID 36671345, 2023). "This study aimed to determine whether salivary CRP levels could help distinguish between bacterial and viral pneumonia in children." (PMID 37189569, 2023). "In children, the CRP/MPV ratio might be used in differentiating bacterial from viral pneumonia and prediction of complications." (PMID 34708133, 2021). "In addition, increased C-reactive protein (66.1% vs. 14.3%, P < 0.001) and erythrocyte sedimentation rate (82.2% vs. 14.3%, P < 0.001) were also more common in viral pneumonia cases than in mild URTI cases." (PMID 33690662, 2021). "Misclassifications of this type would result in overestimating the proportion of RSV pneumonia cases with elevated CRP, and thus the specificity of CRP for detecting bacterial compared to viral pneumonia may be higher." (PMID 28575375, 2017). "Ten studies compared CRP levels in bacterial versus viral pneumonia patients." (PMID 27486746, 2016).
viral pneumonia (continued). "This study was performed to demonstrate the effects of methylprednisolone (MPS) and azithromycin treatment on serum biochemical factors and their impact on Serum Biochemical Factors (CRP, PCT, IL-6, TNF-a) prognosis in patients with viral pneumonia (VP)." (PMID 40821637, 2025). "Viral pneumonia has been predicted by IL6, IL27, and CRP, with distinct cytokine expression profiles differentiating viral from bacterial community-acquired pneumonia." (PMID 41373577, 2025). "In previous work, we have also discovered increased serum level of IL-10, IL-6, as well as acute-phase proteins (CRP and Serum amyloid A1) in the same patients with SARS-CoV-2 induced viral pneumonia." (PMID 36298646, 2022). "In pediatrics, the CRP/MPV ratio can be used as a marker for the differential diagnosis between bacterial and viral pneumonia as well as the prediction of complications." (PMID 34708133, 2021). "There are conflicting reports on the utility of serum inflammatory biomarkers such as CRP, WCC, and ANC for differentiating bacterial from viral pneumonia in children." (PMID 30940126, 2019). "In our study, PCT levels were similar in mixed and bacterial CAP, and higher than those of viral CAP, and in terms of CRP, we found that mixed CAP showed significantly higher levels than bacterial and viral pneumonias." (PMID 25073709, 2014). "Additionally, CRP and AGE play crucial roles in the diagnosis of viral pneumonia, which is consistent with the findings of this study." (PMID 40669043, 2025). "In addition, the best model we developed indicated that the identification of cold and hot syndromes in viral pneumonia is closely related to 13 features: temperature, RDW-SD, CREA, TBIL, GLO, CRP, IBIL, WBC, NEU%, AST/ALT, TCHO, PCT, and AGE." (PMID 40669043, 2025). "Both in men and in women, the CRP/Neopterin ratio was able to distinguish between viral and bacterial pathogens, but also was able to detect bacterial super-infection (BSI) in subjects with initial viral pneumonia (p < 0.001)." (PMID 38930481, 2024). "While some studies have demonstrated greater CRP levels in bacterial than in viral pneumonia, others have not." (PMID 37275364, 2023). "Capitalizing on these findings, we show that levels of S100A9 were significantly increased in BALF of patients with bacterial (including pneumococcal) but not viral pneumonia and positively correlated with CRP, PCT and SOFA scores." (PMID 37467233, 2023). "This study showed that the salivary CRP level was not helpful in differentiating between bacterial and viral pneumonia in children." (PMID 37189569, 2023). "For viral pneumonia, dyspnea plus respiration rates > 20/min had good predictive capacity regardless of CRP concentration." (PMID 36253753, 2022). "The CRP to PCT ratio differed between atypical and viral pneumonia (120.4 vs. 38, respectively)." (PMID 36233374, 2022). "This is consistent with our validation results that dyspnea plus respiration rates > 20/min had good predictive capacity for viral pneumonia even without the result of CRP concentration." (PMID 36253753, 2022). "For viral pneumonia, dyspnea plus respiration rates > 20/min had good predictive capacity even without the result of CRP concentration." (PMID 36253753, 2022). "A study of children found that compared to CRP concentration ≥ 72 mg/L alone, CRP ≥ 72 mg/L combined with symptoms (including rhinorrhea) could improve the specificity and PPV in discriminating bacterial from viral pneumonia." (PMID 34583675, 2021). "Several studies have found higher CRP levels in bacterial than viral pneumonia, whereas others have not." (PMID 28575375, 2017). "In pediatric patients, serum CRP was not useful to distinguish between classical bacterial, atypical or viral pneumonia." (PMID 19594893, 2009).
viral pneumonia (continued). "Thus, other laboratory findings, such as CRP levels, erythrocyte sedimentation rate (ESR), and elevated lactate dehydrogenase levels, were used to establish a correlation as surrogate variables to discriminate between bacterial from viral pneumonia." (PMID 37068086, 2023). "In addition, our results showed that dyspnea plus respiration rates > 20/min had a good predictive capacity for viral pneumonia regardless of CRP concentration." (PMID 36253753, 2022). "Moreover, S100A9 protein levels were positively correlated with C reactive protein (CRP) in BALF of patients with bacterial but not viral pneumonia (Pearson’s r = 0.54, p-value = 0.03 for bacterial versus viral pneumonia with Pearson’s r = -0.76, p-value = 0.01)." (PMID 37467233, 2023). "The levels of C-reactive protein did not significantly differ between NCRD and CRD; nor between the CRD subgroups; this could be explained by the fact that in the context of viral pneumonia this biomarker tends to fall in the normal range and not be useful for determining prognosis." (PMID 34149705, 2021).
diverticulitis (52 papers, 2013 to 2025). An infection that develops in the diverticula of the intestinal tract. "Based on the findings of this study, while the Hinchey classification remains a valuable guide for evaluating complicated diverticulitis, its diagnostic accuracy can be further enhanced when used alongside inflammatory markers such as sodium, CRP, and WBC." (PMID 40282883, 2025). "The mechanism behind intestinal perforation involves TCZ, potentially masking abdominal pain and suppressing the elevation of CRP, thus impeding the healing process of intestinal injuries caused by diverticulitis." (PMID 40066438, 2025). "In summary, for diverticulitis, particularly complicated cases, CRP is the preferred biomarker due to its diagnostic reliability, while LC and NC provide additional valuable information." (PMID 40067493, 2025). "Previous studies have found CRP to be an important parameter for predicting the risk of complicated diverticulitis, although a predictive cutoff value (range 93–175 mg/L) has not been agreed upon." (PMID 39115694, 2024). "The authors concluded that patients with a CRP value higher than 150 mg/l have an increased risk of complicated diverticulitis and should always undergo a CT examination." (PMID 32381121, 2020). "In multivariate analysis, a CRP value over 150 mg/l and old age were independent risk factors for acute complicated diverticulitis." (PMID 27478494, 2016). "Furthermore, blood CRP values have been linked to the clinical and histological severity of diverticulitis." (PMID 36978310, 2023). "In our patient cohorts, we confirmed CRP as an independent risk factor for complicated AD, and a lower cut-off (CRP > 80 mg/L) was selected for the PACO-diverticulitis score in order to increase its predictability when combined with the other selected items of the score." (PMID 33572940, 2021). "All studies found a significant effect of CRP level on the risk of complicated diverticulitis." (PMID 28799055, 2017). "Four studies reported on CRP level as a risk factor for complicated diverticulitis." (PMID 28799055, 2017). "There was reasonable quality of evidence suggesting that high C-reactive protein; white blood cell count; clinical signs including generalized abdominal pain, constipation and vomiting; steroid usage; a primary episode; and comorbidity are risk factors for complicated diverticulitis." (PMID 28799055, 2017). "Additional research corroborates that parameters such as procalcitonin and CRP serve as crucial markers for differentiating between complicated and uncomplicated diverticulitis." (PMID 40387926, 2025). "Conversely, other studies have emphasized that CRP can be used as an effective marker for predicting the severity of acute diverticulitis, recommending mandatory CT imaging in patients with CRP levels ≥ 150 mg/L." (PMID 40282883, 2025). "In the context of acute uncomplicated diverticulitis (AUD), CRP is especially valuable due to its association with disease severity, treatment response, and risk of complications." (PMID 41517338, 2025). "CRP is the most effective biomarker for diagnosing both uncomplicated and complicated diverticulitis, exhibiting high sensitivity and perfect NPV." (PMID 40067493, 2025). "We found that CRP levels were significantly higher in the complicated diverticulitis group, with a mean value of 86.5 mg/L." (PMID 40282883, 2025). "While studies have reported significantly higher WBC levels in patients with complicated diverticulitis, the specificity and sensitivity of this marker remain lower compared to other inflammatory markers, such as CRP." (PMID 40282883, 2025). "C-reactive protein (CRP) outcomes were reported in three studies conducted in acute uncomplicated diverticulitis." (PMID 41517338, 2025). "Studies investigating inflammatory markers such as CRP from blood samples in the diagnosis of acute diverticulitis and the identification of complications have reported varying results and threshold values." (PMID 40282883, 2025).